MIR4300HG (MIR4300 host gene)
Gene: Long non-coding RNA gene on chromosome 11 (81,821,272 to 82,718,299, reverse strand). Ensembl gene ENSG00000245832.
Diseases named in the same sentence as MIR4300HG in open-access papers:
MIR4300HG is named in the same sentence as 1 disease in open-access papers, as found by Europe PMC text mining. Sharing a sentence is not in itself a finding about the gene and the disease.
MIR4300HG shares sentences with these, for which no sentence is quoted: Alzheimer disease (1 paper).